PALB2 (partner and localizer of BRCA2)
Diseases named in the same sentence as PALB2 in open-access papers (continued):
Sharing a sentence is not in itself a finding about the gene and the disease.
cancer (continued). "The single PPTP/C pediatric model (KT-10) with a homologous recombination deficiency (HRD) mirrors the clinical setting in which genetic loss of BRCA1/2, BARD1, PALB2, and other genes associated with HRD is uncommon in pediatric cancers." (PMID 39510293, 2024). "Our work reveals a previously unappreciated role of the RAD18, UBC13, PALB2 and RNF168 pathway in replication fork recovery in BRCA1-deficient cancer cells." (PMID 38943334, 2024). "Although 58.3% of women with a mutation had several relatives with various types of cancer, segregation analysis was performed in some families with index cases having P/LP variants in BRCA2, ATM, and PALB2 genes." (PMID 38890714, 2024). "We next explored the effect of ANM-associated genes on cancer outcomes, replicating previously reported associations with PTVs in BRCA2, CHEK2 and PALB2 and cancer outcomes in male and female subjects." (PMID 39261734, 2024). "It was recently demonstrated that PRS created meaningful risk gradients among female carriers of PVs in cancer-predisposing genes other than BRCA, including ATM, CHEK2, PALB2, BARD1, BRIP1, CDH1, and NF1." (PMID 38339330, 2024). "Cisplatin followed by olaparib, larotrectinib or entrectinib, and pembrolizumab are recommended for BRCA1/2- or PALB2-mutated cancers, NTRK gene-fusion-positive cancers, and MSI-H/dMMR cancers respectively." (PMID 38467634, 2024). "It is well established that cancer risk is modified by family history (BRCA1/2; PALB2; RAD51C and RAD51D (RAD51C/D))." (PMID 38443545, 2024). "Knowledge for the origin of human PALB2 germline PVs is important to understand the biological basis of PALB2 germline PVs in cancer." (PMID 37511102, 2023). "In major studies, 18 target genes such as BRCA1,BRCA2, and PALB2 were reported as biomarkers for cancer progression and development." (PMID 39430039, 2023). "The median age for cancer diagnosis across the BRCA1/2 mutation carriers was 46 years, in the CHEK2 group it was 42.5 years, 44.8 years for ATM, 48.6 years for PALB2, 44 years for MUTYH, and 45.6 years for BLM." (PMID 38201513, 2023). "PARPi activity was also demonstrated for BRCAwt cancers due to mutations in genes critical for DNA repair (e.g., ATM, BARD1, BRIP1, CHEK2, NBN, PALB2, RAD51C, and RAD51D)." (PMID 36910637, 2023). "Well‐known cancer critical genes like BRCA1, IDH1, ERG, KMT2C, MSH6 and PALB2 were among the mutated genes in the metastatic samples." (PMID 35880692, 2023). "Data on heterozygote PALB2 disease-causing variant carriers compared to BRCA1/BRCA2 carriers are still scarce in terms of both cancer incidence, spectrum of cancers and clinical outcomes." (PMID 37686625, 2023).
cancer (continued). "FA displays an autosomal recessive inheritance, but cancer risk is associated with some heterozygous mutations in the following genes: BRCA2 (FANCD1), BRIP1 (FANCJ), PALB2 (FANCN), RAD51C (FANCO), BRCA1 (FANCS)." (PMID 37239385, 2023). "Pathogenic variants in BRCA2/FANCD1, PALB2/FANCN, BRIP1/FANCJ, and RAD51C/FANCO have known adult-onset cancer risks, and there are recommendations for carriers to have increased cancer surveillance, consider chemoprevention, or undergo preventative surgeries." (PMID 35359366, 2022). "Physicians treating patients with cancer should be alert of the FANCD1/BRCA2 and FANCN/PALB2 associated malignancies and consider the possibility of FA diagnosis." (PMID 36091172, 2022). "Cancer-associated germline variations, namely ATM p.Lys468fs and PALB2 c.2835-1G>C, were detected in 2 of 56 patients with solid pseudopapillary tumors (3.6%)." (PMID 35171259, 2022). "In a large cohort of the Chinese cancer population, the frequency of reversion mutations in pan-cancer unselected patients was 1.7%, with the most events reported in BRCA1, BRCA2, and PALB2 genes." (PMID 36557020, 2022). "A second germline variant was found in PALB2, CHEK2, ATM, and NBN, and they presented an additional cancer at the ages of 37, 57, 52, and 58, respectively." (PMID 36003761, 2022). "Genetic loci associated with other cancers and cancer syndromes, including BRCA2 and PALB2, are also associated with PDAC." (PMID 36077772, 2022). "For each patient, we also showed the risk in the well-known high-penetrance cancer risk alleles BRCA1 and BRCA2 with respect to other moderate-penetrance alleles including PALB2, CHEK2, ATM, BARD1, RAD51D, RAD51C and BRIP1." (PMID 35886069, 2022). "In this report we did a pan-cancer analysis using data reported on the Catalogue of Somatic Mutations in Cancers (COSMIC) to identify double mutants between RAD52 and BRCA1, BRCA2 or PALB2 that occur in cancer cells." (PMID 36107942, 2022). "Patients with biallelic PVs in FANCD1/BRCA2 or FANCN/PALB2 should have cancer surveillance at very young age, particularly focused on the associated cancers." (PMID 36091172, 2022). "Studies on genetic predisposition to cancer diseases revealed the existence of a number of founder alleles and recurrent mutations in several genes, including BRCA1, CHEK2, and PALB2 genes." (PMID 35313928, 2022). "We also identified medically actionable variants in eight other cancer-related SFs genes, including APC, MAX, MSH6, MLH1, PALB2, PMS2, SDHB, and TSC2." (PMID 36143288, 2022). "In total, 17 (94%) of the variants were private to a single person and were mostly related to cancer predisposition genes such as MUTYH, MSH6, BRCA2, and PALB2." (PMID 35562925, 2022). "Of the patients, 73.2% underwent genetic testing, and 30% of them presented germline likely pathogenic or pathogenic variants in cancer predisposition genes (24 BRCA1, 4 BRCA2, 1 PALB2, 1 NBN, and 1 ATM)." (PMID 36531080, 2022). "Such an outcome would lend further support to the potential use of autophagy inhibition to treat PALB2 and BRCA1 mutant cancers and possibly other cancers associated with DNA damage and oxidative stress." (PMID 40396054, 2022). "Here, we summarize the main findings and discuss their implications in neurodegeneration and the potential treatment of PALB2 mutant and similar cancers with autophagy inhibition." (PMID 40396054, 2022). "Their findings disclosed a significant enrichment (0.44%) of germline FANCN/PALB2 PVs in three out of 680 unselected CRC patients versus the cancer-free control population." (PMID 35330396, 2022). "To further explore the role of PALB2 in cancers, we performed a pan-cancer analysis of PALB2 in 33 types of cancers." (PMID 36158641, 2022). "Core (BRCA1/2, PALB2), and any HRR mutations (BRCA1/2, PALB2, CHEK2, FANCA, ATM) occurred in 13 (10.3%) and 22 (17.5%) cancers, respectively." (PMID 36124727, 2022).
cancer (continued). "To further understand the effect of PALB2 expression on prognosis, we performed a pan-cancer analysis of the relationships between PALB mRNA level and prognosis in 33 tumor types." (PMID 36158641, 2022). "But the most remarkable pro-cancer RAD52 phenotype is seen in cancer cells deficient in any of the following DNA repair proteins: BRCA1, BRCA2, PALB2, XAB2 or RAD51 paralogs: RAD51B, RAD51C, RAD51D, XRCC2 and XRCC3." (PMID 34887904, 2021). "A small, but unique group of 16 non-FAP mesenteric desmoid was found to harbor genetic alterations in cancer associated genes other than APC, including CHEK2, BLM, ERCC5, MSH6, and PALB2." (PMID 34359575, 2021). "This literature review addresses cancer predisposition genes, including BRCA1, BRCA2, and PALB2, synthetic lethality in the context of DNA repair machinery, as well as available treatment options." (PMID 34070674, 2021). "The presence of Signature 3 in cases with BRCA1, PALB2 and RAD51C variants, as well as tumor enrichment of these variants, suggest that these cancers are HR-deficient." (PMID 33917078, 2021). "Topoisomerase 1 inhibitors have been shown to be effective in cancer therapy of HR-deficient, Schlafen 11-positive cells in association with Olaparib, for the treatment of BRCA1-, BRCA2-, and PALB2-deficient cells." (PMID 34639169, 2021). "For women with a PALB2, CDH1 or NF1 mutations, the NCCN recommends an annual mammogram and annual MRI beginning at age 30, unless the age of cancer diagnosis within the family was earlier." (PMID 34573353, 2021). "Since loss-of-function variants in the BRIP1 and PALB2 genes increase the risk of BC and OC28,29, these variants were considered to be the main cause of the increased cancer risk in these two families." (PMID 34282249, 2021). "This literature review addresses cancer predisposition genes, including BRCA1, BRCA2, and PALB2; synthetic lethality in the context of DNA repair machinery; and historical and current treatment options for breast and ovarian malignancies with these mutations." (PMID 34070674, 2021). "The genes selected included epithelial (KRT5, CDH1, EpCAM), mensenchymal (VIM, SNAI1, TWIST), stem (ALDH1A1, PROM1), breast specific (ESR1, PALB2) and other genes related to cell cycle or other cancer pathways (CCND1, CTNNB1, Ki67, etc.)." (PMID 34071445, 2021). "LOH of BRCA1/2, RAD51C or PALB2 was also found as a monoallelic event, mainly in ovarian (47%) and breast (49%) cancer patients." (PMID 33149131, 2020). "For instance, we found PALB2 in Cancer, JAK-STAT pathway in ‘Digestive System Disorder’ and LPL (Lipoprotein Lipase) in ‘Lipid or Lipoprotein Measurement’." (PMID 32678846, 2020). "Secondary mutations across various cancer types were discovered to cause the reversion of DDR protein or gene function, such as BRCA1/2, PALB2, and RAD51C/D, resulting in the restoration of HR repair function and nullifying synthetic lethality." (PMID 32883316, 2020). "The fact that most the PALB2-HET BC tumors also exhibit known cancer drivers suggests either tumor evolution or this demonstrates the well known phenomenon of differential positive selection." (PMID 33193564, 2020). "Family members of patients with FA who are heterozygous carriers of PV in genes from the fourth module FANCD1 (BRCA2), FANCJ (BRIP1), FANCN (PALB2), FANCO (RAD51C) and FANCS (BRCA1) are at increased risk to develop cancer." (PMID 33371494, 2020). "Six pathogenic variants (in BRCA1,BMPR1A,FANCA,FANCC,NBN genes) with cancer related phenotype and three unsolicited variants (in BRCA2,PALB2,RAD50 genes) were reported to patients." (PMID 31937788, 2020).
cancer (continued). "The known genotypes of these patients are either FANCD1 (BRCA2) or FANCN (PALB2), in whom cancer usually occurs in the first decade of life." (PMID 33371494, 2020). "Instead, we relied on an homologous complementation system where human PALB2 was expressed in human cancer cell lines depleted for PALB2." (PMID 31586400, 2019). "Similar to what has been described for BRCA2, loss of functional PALB2 is synthetic lethal with poly(ADP-ribose) polymerase (PARP) inhibitors, an innovative class of anti-cancer drugs." (PMID 31586400, 2019). "Inhibiting these signalizations can be considered as an approach for sensitizing cells to DNA damaging agents, which provides an opportunity to develop a putative target, PALB2, for accessing cancer treatment." (PMID 30975222, 2019). "PALB2, ALDH1A3, and IGF1R were reported to show associations with sensitivity to mitomycin, stem cell markers, and cancer progression, respectively." (PMID 30719229, 2019). "This indicates that both the interaction with BRCA1 and BRCA2 is crucial for PALB2’s function in controlling G2/M-phase progression following DNA damage, which is in accordance with observations in human cancer cells." (PMID 31757951, 2019). "Thus, our functional assays identify damaging VUS in PALB2 that may increase cancer risk." (PMID 31757951, 2019). "In human cancer cell-lines with defective function of BRCA1, PALB2 or BRCA2, RAD52′s depletion increases damage-associated chromosomal abnormalities, decreases clonal viability, and also reduces the HR activity." (PMID 31652722, 2019). "A growing body of evidence suggests that PALB2 functions as a tumor suppressor, which is being explored as targets for development of therapies strategies against cancer." (PMID 30975222, 2019). "The in vitro studies suggested that PALB2 knockdown will decrease the migration ability of the cells and overexpression of PALB2 increase the migration or invasion ability of the cancer cells." (PMID 29321957, 2018). "Cancers harboring mutations in “BRCAness” genes, including BRCA1, BRCA2, ATM and PALB2, have been found to be sensitive to DNA crosslinking agents." (PMID 29515757, 2018). "Mutations in genes of the breast cancer susceptibility gene (BRCA) pathway, namely, BRCA1, BRCA2, and PALB2, can provide useful information for the efficacy of platinum-based or poly ADP-ribose polymerase inhibitors chemotherapeutic regimens." (PMID 29802286, 2018). "The rarity of mutations in PALB2, CHEK2 and ATM make it difficult to estimate precisely associated cancer risks." (PMID 27595995, 2016). "Recent studies have highlighted importance of RAD52 in human cancer cell lines deficient in BRCA1, PALB2 or BRCA2, as its depletion led to cell death in a synthetic lethality manner." (PMID 26610585, 2015). "The association of ‘early’ FA genes with FANCD2 monoubiquitination defects with increased cancer susceptibility is much weaker compared with the ‘late’ FA genes such as BRCA1, BRCA2, BRIP1, PALB2 and RAD51C." (PMID 26085575, 2015). "We focused on identifying mutations in BRCA1, BRCA2 and PALB2 and the CHEK2 c.1100delC mutation, as the risks for the development of breast and associated cancers with these genes have been determined by analysing large study populations." (PMID 26577449, 2015). "We observed several significant associations in specific cancer types: RAD51C in AML, ATM in PRAD and PALB2 in STAD." (PMID 26689913, 2015).
cancer (continued). "Amino acids 1 to 40 interact with PALB2, and sequence variants in this region have been shown to have effects on the PALB2 and BRCA2 interaction and thus are suspected to have a role in cancer predisposition." (PMID 21356067, 2011). "In addition, other molecular changes may cooperate with PALB2 deficiency in cancer development." (PMID 20122277, 2010). "Genetic testing was negative for BRCA1/2, CHEK2, and PALB2 mutations, though familial cancer history suggested a possible hereditary syndrome (FCC suspicion)." (PMID 40926949, 2025). "Other homologous recombination DNA damage repair (HR-DDR) genes associated with other cancer risks besides breast and ovarian, such as ATM (n = 9), BARD1 (n = 4), BRIP1 (n = 2), CHEK2 (n = 5), PALB2 (n = 5), RAD51C (n = 1), and RAD51D (n = 7), accounted for an additional 4% (33/769)." (PMID 40065011, 2025). "While most heterozygous carriers do not appear to have significantly increased cancer risks, susceptibility to cancer, including CRC, is well established for carriers of heterozygous pathogenic variants in FANCS/BRCA1, FANCD1/BRCA2, FANCN/PALB2, FANCJ/BRIP1, and FANCO/RAD51C." (PMID 41155398, 2025). "Women may be at high risk due to a family history of cancer or a pathogenic or likely pathogenic variant in a cancer-susceptibility gene (such as BRCA1, BRCA2, or PALB2)." (PMID 38611036, 2024). "Pathogenic variants of ATM (ataxia-telangiectasia mutated), CHEK2 (checkpoint kinase 2), PALB2 (partner and localizer of BRCA2), and XRCC2 (X-ray repair cross-complementing 2) tumor suppressor genes (TSGs) have been associated with the development of cancers." (PMID 38784039, 2024). "Together with previous results, these findings further suggest that haploinsufficiency of PALB2 or BRCA2 can be a potential initiating event for malignant changes in these heterozygous cell models, and possibly also in cancers associated with such disease predisposition." (PMID 38597967, 2024). "The ability of PALB2-mutated cells and spheroids to agglomerate could also protect them against the KRT14 KD, since cluster formation can considerably increase cancer cell survival." (PMID 38597967, 2024). "Cancer cells may also acquire additional mutations in other DNA repair genes in the HRR pathway, such as PALB2, which may compensate for the loss of BRCA function." (PMID 39796639, 2024). "Therefore, appropriate prevention and treatment strategies for PALB2 related cancer will also be needed in Koreans." (PMID 39409938, 2024). "Only one study included East European and, thus, Romanian cancer-diagnosed patients, but with no detailed description of PALB2 mutation." (PMID 37239058, 2023). "We prospectively evaluated the prevalence of germline PALB2 genetic variants in 1848 (1280 breast and 568 non-breast) consecutive Hungarian cancer patients between 2021 September and 2023 March." (PMID 37686625, 2023).